AXIN2 (axin 2)
Description:
Inhibitor of the Wnt signaling pathway. Down-regulates beta-catenin. Probably facilitate the phosphorylation of beta-catenin and APC by GSK3B.
Synonyms: Axil; MGC126582; DKFZp781B0869; ODCRCS
Tractability: Small molecule: it belongs to a druggable protein family. Antibody: its Gene Ontology location is reachable by antibodies, with medium confidence. PROTAC: UniProt records ubiquitination sites on it; ubiquitination databases record sites on it; a small molecule that binds it is known.
Chemical probes: HLY78
Gene: Protein-coding gene on chromosome 17 (65,528,561 to 65,562,067, reverse strand). Ensembl gene ENSG00000168646.
Subcellular location: Cytoplasm
Subcellular location (Human Protein Atlas): Cytosol; Nucleoplasm; Plasma membrane
Pathways (Reactome):
Signal Transduction: Binding of TCF/LEF:CTNNB1 to target gene promoters; Ca2+ pathway; Degradation of AXIN; Repression of WNT target genes; TCF dependent signaling in response to WNT
Chromatin organization: CHD6, CHD7, CHD8, CHD9 subfamily
Metabolism of proteins: Ub-specific processing proteases
Gene Ontology:
Molecular function: enzyme binding; protein binding; ubiquitin protein ligase binding; beta-catenin binding; I-SMAD binding; molecular adaptor activity; protein kinase binding
Biological process: canonical Wnt signaling pathway; intracellular protein localization; maintenance of DNA repeat elements; mRNA stabilization; negative regulation of canonical Wnt signaling pathway; odontogenesis; positive regulation of epithelial to mesenchymal transition; regulation of centromeric sister chromatid cohesion; regulation of mismatch repair; aortic valve morphogenesis; cell development; mitral valve morphogenesis; positive regulation of proteasomal ubiquitin-dependent protein catabolic process; proteasome-mediated ubiquitin-dependent protein catabolic process; regulation of extracellular matrix organization; cellular response to dexamethasone stimulus; dorsal/ventral axis specification; negative regulation of cell population proliferation; negative regulation of Wnt signaling pathway; positive regulation of fat cell differentiation; response to steroid hormone
Cellular component: centrosome; cytoplasm; cytosol; nucleus; beta-catenin destruction complex; plasma membrane; protein-containing complex
Genetic constraint (gnomAD): Loss-of-function variants: 21 observed, 76.16 expected, observed/expected ratio (o/e) 0.28, 90% interval 0.19 to 0.4. The upper end of that interval is the gene's LOEUF score, 0.4, which puts it in group 1 of 6, group 1 being the genes least tolerant of losing a copy. Missense variants: 1,144 observed, 1,142.8 expected, observed/expected ratio (o/e) 1, 90% interval 0.95 to 1.05. Synonymous variants: 532 observed, 470.47 expected, observed/expected ratio (o/e) 1.13, 90% interval 1.05 to 1.22.
Gene-disease validity (ClinGen):
ClinGen rates the evidence that AXIN2 causes each of these diseases.
oligodontia-cancer predisposition syndrome (autosomal dominant): Definitive.
Cancer hallmarks: suppression of growth (promotes)
Homologues: Orthologues: chimpanzee AXIN2 (99% identical), macaque AXIN2 (98% identical), dog AXIN2 (93% identical), pig AXIN2 (92% identical), rat Axin2 (90% identical), mouse Axin2 (90% identical), guinea pig AXIN2 (85% identical), rabbit AXIN2 (81% identical), zebrafish axin2 (63% identical), tropical clawed frog axin2l (38% identical). Paralogues in human: AXIN1 (45% identical), RGS12 (13% identical), RGS14 (11% identical), RGS9 (10% identical), RGSL1 (9% identical), RGS22 (9% identical), RGS3 (7% identical), RGS11 (7% identical), RGS6 (7% identical), RGS18 (6% identical), RGS7 (6% identical), RGS1 (6% identical), and 11 more.
Diseases named in the same sentence as AXIN2 in open-access papers:
AXIN2 is named in the same sentence as 189 diseases in open-access papers, as found by Europe PMC text mining. Sharing a sentence is not in itself a finding about the gene and the disease. The quoted sentences say what the papers report.
colorectal cancer (92 papers, 2004 to 2026). A primary or metastatic malignant neoplasm that affects the colon or rectum. "Seeking orthogonal evidence, we examined the change in AXIN2 expression for the collection of MSS colorectal cancers for which both mutational and RNA sequencing (RNA-seq) data were available (n = 89 samples from 100kGP; n = 243 samples from TCGA)." (PMID 41091816, 2025). "Our data show that AXIN2‐mediated feedback inhibition of the Wnt pathway is active in APC mutated colorectal cancer cells." (PMID 39022865, 2025). "Germline loss-of-function variants in AXIN2 are also reported to be associated with colonic polyposis and colorectal cancers." (PMID 38647838, 2024). "Axin2, as a target gene of the Wnt signaling pathway, was previously categorized as a tumor suppressor gene in a small fraction of colorectal cancers harboring APC gene mutations." (PMID 35875099, 2022). "AXIN2 has more recently been described to be associated with colorectal cancer, and therefore, the association with breast cancer is not well understood." (PMID 33413596, 2021). "Axin2 mutations are also linked to malignancy, most notably colorectal cancer, due to its detection in a Finnish family in which several members suffered from tooth agenesis and colonic neoplasia." (PMID 34858573, 2021). "Axin2 is thus a risk factor for oligodontia-colorectal cancer syndrome, predisposing patients to colorectal cancer and oligodontia." (PMID 34858573, 2021). "These genes, when impaired, have been associated to increased risk of colorectal cancer (both) and breast cancer (AXIN2)." (PMID 34262869, 2021). "A recent interrogation of the cBioPortal for Cancer Genomics database highlights APC, AXIN2, and β-catenin mutations in ≈67%, ≈5%, and ≈6% of colorectal carcinomas, respectively." (PMID 34352208, 2021). "AXIN2 is also considered a tumor suppressor and mutations in the human gene coding this protein have been linked to colorectal carcinoma." (PMID 34072517, 2021). "A nonsense mutation in AXIN2 (p.Arg656*) was previously found to cause oligodontia and a predisposition to colorectal cancer in a four-generation Finnish family." (PMID 32234057, 2020). "Recent research manifested that the aberrant activation Wnt/β-catenin signaling pathway was closely related to colon cancer, and the mutation of Wnt signaling pathway genes (Apc, Axin2) were found in mostly intermittent colorectal cancer." (PMID 31164916, 2019). "A germline nonsense mutation in AXIN2 (c.1996C > T, p.Arg656*) was identified as the likely cause of autosomal dominant oligodontia (severe TA) and colorectal cancer segregating in a large, four-generation Finnish family." (PMID 29772684, 2018). "It is suggested that truncating pathogenic variants in AXIN2 are more likely to predispose carriers to syndromic oligodontia and colorectal cancer compared to missense variants." (PMID 27696107, 2017). "Intriguingly, a pathogenic AXIN2 mutation has been described as causative for both TA and cancer development in a Finnish family where the TA phenotype segregated with colorectal cancer predisposition." (PMID 27699475, 2016). "The AXIN2 gene has been mapped at human chromosome 17q23-q24, which shows frequent loss of heterozygosity (LOH) in cancers, and mutations in the AXIN2 gene are associated with colorectal cancer with defective mismatch repair." (PMID 26161041, 2015). "Axin2 negatively regulates Wnt/β-catenin signaling and mutations in Axin2 have been described to be oncogenic in colorectal cancer." (PMID 25950950, 2015). "Two mutations in exon 7 of AXIN2 gene have been related with severe forms of tooth agenesis and predisposition to colorectal cancer." (PMID 24316698, 2014). "It was also reported than mutations in AXIN2 cause colorectal cancer with defective mismatch repair by activating β-catenin or TCF signaling." (PMID 25242495, 2014).
colorectal cancer (continued). "The mutations and loss of heterozygosity in AXIN2 gene have been identified in various cancers, including lung cancer, hepatocellular neoplasm, and colorectal carcinomas." (PMID 24695522, 2014). "MSX1 and AXIN2 genes, involved in the early stages of odontogenesis, are associated with tooth agenesis in individuals with disorders such as cleft palate and colorectal cancer." (PMID 24319602, 2013). "Inactivating mutations and epigenetic silencing of AXIN2 have been previously reported to be involved in MSI colorectal cancer, mainly by deregulating the Wnt signaling pathway." (PMID 22159500, 2012). "AXIN2 aberrations cause multiple missing teeth, intestinal polyposis, and predispose to colorectal cancer." (PMID 23227268, 2012). "AXIN2 gene mutations have been described in 11 colorectal cancers, one endometrioid ovarian adenocarcinoma and two hepatocellular carcinomas." (PMID 14970870, 2004). "Furthermore, low RNF43 and AXIN2 levels indicate the involvement of β-catenin activation in inflammatory bowel disease-associated colorectal cancer development." (PMID 41487817, 2025). "Concordantly, loss of AXIN2 disrupted regulation of AXIN1 expression by TNKS in SW480 colorectal cancer cells, which may have therapeutic implications for colorectal cancer through TNKS inhibitors." (PMID 39022865, 2025). "Studies showed that the abundant expression of Axin2 was significantly associated with the malignant transformation of oral leukoplakia, and both Wnt signaling and the invasive ability of cancer cells were attenuated by Axin2 knockdown in colorectal cancers." (PMID 36324094, 2022). "In consequence, the polymorphism in AXIN2 gene may be considered a biological risk marker for predisposition and prognosis of colorectal cancer." (PMID 34378652, 2021). "It has been reported the association of AXIN2 gene with colorectal cancer." (PMID 34378652, 2021). "Similarly, a mutation in AXIN2 identified in colorectal cancers promotes GSK3β inhibition and stabilization of Snail, a positive regulator of Wnt signaling." (PMID 34552611, 2021). "Understanding the association between dental health and colorectal cancer may be critical for screening, but to date, Axin2 is relatively unknown and oligodontia-colorectal cancer syndrome has not been well described." (PMID 34858573, 2021). "Mutation of ZNRF3, a Wnt signaling suppressor, is often found in adrenocortical carcinoma, while AXIN2 mutations induce a predisposition to colorectal cancer, its mutations are detected in colorectal cancer, finally leading to the accumulation of beta-catenin in the nuclei." (PMID 34488905, 2021). "AXIN2 was selected as a strong candidate gene for several reasons: Its position within this particular chromosomal region, a previously identified association with colorectal carcinoma and the fact that AXIN2 is also a known regulator of the Wnt signalling pathway." (PMID 24121910, 2014). "Thus, AXIN2 restricts Wnt signaling to some extent even in APC mutated colorectal cancer cells." (PMID 39022865, 2025). "AXIN1 and AXIN2 are homologous proteins that inhibit the Wnt/β‐catenin signaling pathway, which is frequently hyperactive in colorectal cancer." (PMID 39022865, 2025). "Because our data pointed to an essential role for AXIN2 in regulating the Wnt pathway in colorectal cancer cells, we investigated the particular relevance of AXIN2 for Wnt pathway inhibition by TNKS small‐molecule inhibitors in these cells." (PMID 39022865, 2025). "TNKS small‐molecule inhibitors block Wnt/β‐catenin signaling by stabilizing AXIN1 and AXIN2, and have therefore been investigated for targeted treatment of colorectal cancer." (PMID 39022865, 2025). "Consistently, AXIN2 knockout clones exhibited elevated β‐catenin protein levels, demonstrating that loss of AXIN2 impairs degradation of β‐catenin in APC mutant colorectal cancer cells." (PMID 39022865, 2025).
colorectal cancer (continued). "Here, we found that knockout or knockdown of AXIN2 in colorectal cancer cells increased the protein stability of AXIN1." (PMID 39022865, 2025). "Our mechanistic studies with transiently expressed proteins suggest that AXIN2 promotes TNKS‐mediated degradation of AXIN1 in colorectal cancer cells by increasing TNKS–AXIN1 interaction." (PMID 39022865, 2025). "Our proposed mechanism of AXIN2‐induced degradation of AXIN1 will correlate with the expression levels of AXIN2 and therefore will be most active in colorectal cancer cells expressing high AXIN2 levels." (PMID 39022865, 2025). "Homeobox C6 overexpression reduces the RNF43 and AXIN2 expression levels, leading to a poor prognosis for patients with colorectal cancer." (PMID 41487817, 2025). "In the present study, we noted that knockout or knockdown of AXIN2 in human SW480 colorectal cancer cells resulted in higher protein levels of AXIN1, which was a result of increased protein stability." (PMID 39022865, 2025). "To investigate the activity of the AXIN2 feedback in APC‐mutated colorectal cancer in a clean system, we generated SW480 AXIN2 knockout cells using the CRISPR/Cas9 technique." (PMID 39022865, 2025). "Our experiments revealed that inhibition of Wnt signaling by TNKS small‐molecule inhibitors in SW480 colorectal cancer cells strictly depends on AXIN2." (PMID 39022865, 2025). "Accordingly, in AXIN2-related oligodontia–colorectal cancer syndrome, colorectal cancers are typically diagnosed after the age of 40 years, although polyps can present in adolescence." (PMID 38488796, 2024). "Another study showed that the Axin2 axis suppressed tumor growth and metastasis in colorectal cancer." (PMID 38139000, 2023). "To conclude, the present study revealed possible involvement of hsa-miR-1246 in early colorectal cancer development and regulation of tumor suppressors AXIN2 and CFTR." (PMID 35216222, 2022). "AXIN2 is a negative regulator that suppresses GSK3β-mediated degradation of Snail1 and is proved to exert a promotive effect on colorectal cancer." (PMID 35470736, 2022). "Although Axin2 is considered as a tumor suppressor in colorectal cancer, increased expression has also been shown to induce EMT acting as a tumor promotor." (PMID 35562738, 2022). "And finally, AXIN2 has been consistently classified as a tumor suppressor gene in colorectal cancers both in vivo and in vitro." (PMID 35237578, 2022). "Immunofluorescence and Western blot assays revealed that these conjugates reduced the expression levels of the PI3K-P85, β-catenin, TAB-182, β-actin, AXIN-2, and NF-κB markers that are involved in the β-catenin pathway of colorectal cancer." (PMID 36364474, 2022). "MiR-103/107 expression displays stemness-promoting functions, and a signature of miR-103/107 high and Axin2 low expression profile correlates with poor prognosis in colorectal cancer patients." (PMID 33912452, 2021). "Therefore, the true risk of colorectal cancer in patients with an Axin2 mutation is unknown." (PMID 34858573, 2021). "Increased expression of Axin2 was found after the loss of adenomatous polyposis coli (APC), a key tumour suppressor gene, in colorectal cancer, and the knockdown of Axin2 attenuated oncogenic and Wnt signalling activities in cancer cells." (PMID 33046030, 2020). "Demethylation treatment with azacitidine in HCT116, a colorectal cancer cell line with an RNF43 mutation and comparatively low AXIN2 expression, resulted in increased AXIN2 expression and increased cell death." (PMID 33202731, 2020). "In colorectal cancer patients, miR-103/107 expression correlates inversely with Axin2 expression and a signature of miR-103/107 high and Axin2 low expression profile correlates with poor prognosis." (PMID 31273221, 2019). "Together, our study identifies a novel function of miR-103/107 in promoting colorectal cancer stemness by targeting Axin2 and elucidates the clinical relevance and prognostic value of this axis in colorectal cancer." (PMID 31273221, 2019).
colorectal cancer (continued). "A former study demonstrated that the overexpression of AXIN2 induced a dramatic reduction of β-catenin level in human colorectal cancer cell line SW480." (PMID 29966337, 2018). "The study also disclosed distinct profiles of genes relevant for colorectal cancer such as homeobox genes, transcription factors, growth factors and genes in the Wnt signaling pathway, including AXIN2." (PMID 24964857, 2014). "Lastly, in the colorectal cancer cell line SW480 that also possesses a truncating APC mutation, tankyrase RNAi stabilizes AXIN1, AXIN2, and RNF146 proteins." (PMID 21799911, 2011). "Two of the best-established TCF target genes in intestinal epithelial and colorectal cancer cells are c-myc and AXIN2." (PMID 18627596, 2008). "The AXIN2 gene mutations appear to be present exclusively in tumours with a microsatellite instable phenotype since all AXIN2 mutant colorectal carcinomas and the ovarian endometrioid adencarcinoma were microsatellite instable." (PMID 14970870, 2004). "AXIN2 is highly expressed in colorectal cancer because it is a β‐catenin target gene." (PMID 39022865, 2025). "Thus, the overcompensating increase in AXIN1 protein did not functionally compensate for β‐catenin degradation by AXIN2, pointing to a special importance of AXIN2 for Wnt pathway regulation in colorectal cancer cells." (PMID 39022865, 2025). "Because pathway activation by Wnt ligands plays a role in colorectal cancer, the reduced inhibitability of AXIN2 compared to AXIN1 could potentially explain its special importance." (PMID 39022865, 2025). "Taken together, our data suggest that AXIN2 promotes degradation of AXIN1 through TNKS in colorectal cancer cells by directly linking the two proteins, and these findings may be relevant for TNKS inhibition‐based colorectal cancer therapies." (PMID 39022865, 2025). "miR-195-5p is shown to regulate AXIN2 in colorectal cancer cells." (PMID 39095857, 2024). "Additionally, Ganoderma lucidum impacts the WNT signaling pathway, crucial in colorectal cancer, by inhibiting axis inhibition protein 2 (AXIN2) expression and other downstream targets." (PMID 39494346, 2024). "Axin2 is a β-catenin target that is highly expressed in human colorectal cancer." (PMID 38139000, 2023). "Moreover, GBZ strongly reduced the expression of β-catenin target genes at the protein level (AXIN2) and mRNA level in colorectal cancer cells (AXIN2, LGR5)." (PMID 35115535, 2022). "Among the top genes emerging from limma analysis, we found four genes particularly related to cancer stemness and CRC CSCs: besides the pluripotency factor KLF4, we found three genes were specifically related to colorectal cancer stemness and self renewal, i.e., AXIN2, LGR5 and BMI1." (PMID 36077264, 2022). "Interestingly, AXIN2 is also downregulated by miR-34 in colorectal cancer which should inhibit Wnt signaling but miR-34 targets a number of Wnt activators as well, thus limiting the action of AXIN2." (PMID 34552611, 2021). "Another paper showed that targeting AXIN2 axis could suppress tumor growth and metastasis in colorectal cancer." (PMID 33794810, 2021). "Recently, miR-103/107 were also shown to promote colorectal cancer stemness by targeting AXIN2." (PMID 34552611, 2021). "Indeed, the Wnt/β-catenin pathway is constitutively active in most colorectal cancers, where the loss of function mutation and/or epigenetic silencing of negative regulators like APC, AXIN2, DKK1, or SFRP2 are common facts." (PMID 34063173, 2021). "Caperatic acid (CA) isolated from Platismatia glauca downregulated β-catenin-regulated expression of Axin2 gene in both colorectal cancer cell lines, but lecanoric acid (LeA), obtained from Hypocenomyce scalaris decreased the expression of Axin2 in HCT116 cells just moderately." (PMID 31948092, 2020).